RFX7 (regulatory factor X7)
Description:
Transcription factor. Acts as a transcriptional activator by binding to promoter regions of target genes, such as PDCD4, PIK3IP1, MXD4, PNRC1, and RFX5. Plays a role in natural killer (NK) cell maintenance and immunity. May play a role in the process of ciliogenesis in the neural tube and neural tube closure (By similarity).
Synonyms: RFXDC2; FLJ12994; MRD71
Tractability: PROTAC: ubiquitination databases record sites on it.
Gene: Protein-coding gene on chromosome 15 (56,087,280 to 56,245,103, reverse strand). Ensembl gene ENSG00000181827.
Subcellular location: Nucleus
Subcellular location (Human Protein Atlas): Nuclear membrane; Nucleoplasm
Gene Ontology:
Molecular function: protein binding; RNA polymerase II core promoter sequence-specific DNA binding; sequence-specific double-stranded DNA binding; DNA-binding transcription factor activity, RNA polymerase II-specific; RNA polymerase II cis-regulatory region sequence-specific DNA binding; DNA binding; DNA-binding transcription factor activity
Biological process: positive regulation of transcription by RNA polymerase II; regulation of transcription by RNA polymerase II; positive regulation of DNA-templated transcription; regulation of DNA-templated transcription
Cellular component: chromatin; nucleus
Genetic constraint (gnomAD): Loss-of-function variants: 20 observed, 96.93 expected, observed/expected ratio (o/e) 0.21, 90% interval 0.14 to 0.3. The upper end of that interval is the gene's LOEUF score, 0.3, which puts it in group 1 of 6, group 1 being the genes least tolerant of losing a copy. Missense variants: 1,516 observed, 1,747.5 expected, observed/expected ratio (o/e) 0.87, 90% interval 0.83 to 0.9. Synonymous variants: 599 observed, 620.82 expected, observed/expected ratio (o/e) 0.96, 90% interval 0.9 to 1.03.
Gene-disease validity (ClinGen):
ClinGen rates the evidence that RFX7 causes each of these diseases.
complex neurodevelopmental disorder (autosomal dominant): Definitive. A disorder that involves more than one phenotype associated with the central nervous system, including but not limited to intellectual disability, autism, and seizures (epilepsy).
Homologues: Orthologues: macaque RFX7 (99% identical), chimpanzee RFX7 (95% identical), rabbit RFX7 (95% identical), dog RFX7 (95% identical), pig RFX7 (94% identical), rat Rfx7 (93% identical), mouse Rfx7 (93% identical), guinea pig RFX7 (89% identical), tropical clawed frog rfx7 (69% identical), zebrafish rfx7b (55% identical), zebrafish rfx7a (53% identical), Drosophila melanogaster CG9727 (17% identical). Paralogues in human: RFX5 (13% identical), RFX1 (11% identical), RFX2 (10% identical), RFX6 (10% identical), RFX3 (10% identical), RFX4 (9% identical), RFX8 (4% identical).
Diseases named in the same sentence as RFX7 in open-access papers:
RFX7 is named in the same sentence as 19 diseases in open-access papers, as found by Europe PMC text mining. Sharing a sentence is not in itself a finding about the gene and the disease. The quoted sentences say what the papers report.
lymphoid cancers (3 papers, 2021 to 2024). "The transcription factor regulatory factor X 7 (RFX7) has been identified as a tumor suppressor that is recurrently mutated in lymphoid cancers and appears to be dysregulated in many other cancers." (PMID 39181888, 2024). "Moreover, RFX7 alterations have been associated with chronic lymphocytic leukemia, diffuse large B cell lymphoma, and acute myeloid leukemia in humans and with lymphoma and leukemia in mouse models." (PMID 36864036, 2023). "It has been identified as a putative major cancer driver mutated in 13 to 15 % of Epstein-Barr Virus-negative Burkitt lymphoma, and CRISPR/Cas9-targeting of Rfx7 in a mouse lymphoma model confirmed its function as a tumor suppressor." (PMID 36864036, 2023). "The regulatory factor X 7 (RFX7) just recently emerged as a novel tumor suppressor in lymphoid cancers." (PMID 36864036, 2023). "Contrary to other members of Regulatory Factor X family, RFX7 is poorly characterized but shows a high tumor suppressor potential in lymphoid cancers at least." (PMID 34715892, 2021).
Alzheimer disease (2 papers, 2023). A progressive, neurodegenerative disease characterized by loss of function and death of nerve cells in several areas of the brain leading to loss of cognitive function such as memory and language. "Gene-based rare variant analysis of RFX7 in the Alzheimer’s Disease Neuroimaging Initiative (ADNI) cohort showed trending significance with entorhinal cortex thickness." (PMID 36609403, 2023). "Given that RFX7 has been associated with Alzheimer’s disease and cognitive function, a particularly interesting candidate target is SNYPO encoding for the actin filament regulator synaptopodin, which is important for synaptic plasticity and can facilitate Tau protein degradation." (PMID 36864036, 2023).
breast carcinoma (2 papers, 2021). "Furthermore, RFX7 is upregulated in breast cancer but negatively correlates with metastatic development." (PMID 34715892, 2021).
glioblastoma (2 papers, 2021 to 2026). The most malignant astrocytic tumor (WHO grade IV).
cutaneous melanoma (1 paper, 2022). A primary melanoma arising from atypical melanocytes in the skin. "Lastly, we treated three cutaneous melanoma cell lines with Nutlin-3 for 24 h and investigated the mRNA expression of RFX7, RFX5, PNRC1, PDCD4 and CDKN1A as positive control." (PMID 36139642, 2022).
HCMV infection (1 paper, 2023). "As HCMV infection greatly increased the total RFX7 protein level (input), the immunoprecipitated RFX7 amounts were adjusted to the same level between the mock and the HCMV groups for pRFX7 blotting (IP)." (PMID 36753521, 2023). "Compared with the mock-infected cells, HCMV infection noticeably increased RFX7 phosphorylation (indicated by the pRFX7/RFX7 ratio from IB) in NPCs (IP)." (PMID 36753521, 2023). "In the scr control group, HCMV infection greatly boosted RFX7 and SOCS3 expression in NPCs compared with the mock-infected cells." (PMID 36753521, 2023). "Fourth, RFX7 phosphorylation levels were increased by ectopic UL97 expression and HCMV infection in NPCs." (PMID 36753521, 2023).
lymphoid neoplasm (1 paper, 2023). A neoplasm composed of a lymphocytic cell population which is usually malignant (clonal) by molecular genetic and/or immunophenotypic analysis. "Recurrently mutated in lymphoid neoplasms, the transcription factor RFX7 is emerging as a tumor suppressor." (PMID 36864036, 2023).
malaria (1 paper, 2019). Malaria is a serious and sometimes fatal disease caused by a parasite that commonly infects a certain type of mosquito which feeds on humans. "The function of the transcription factor RFX7 is largely unknown but has been found to be strongly up‐regulated during blood‐stage malaria, and its selection in our 7‐gene signature is therefore likely to be driving the classification of malaria cases." (PMID 31468702, 2019).
sarcoidosis (1 paper, 2023). Sarcoidosis is a multisystemic disorder of unknown cause characterized by the formation of immune granulomas in involved organs. "We found that, unlike their control counterparts, both cardiac and BAL sarcoidosis T cells showed enrichment of memory T cell TF genes (RFX7 and ZEB1), survival and proliferation TF genes (HLF and HIST1H2BN) and type 3 response TF genes (ARNTL and ADARB1)." (PMID 37576111, 2023).
tumor (6 papers, 2019 to 2026). "RFX7 has recently emerged as a tumor suppressor that is recurrently mutated in hematopoietic cancers." (PMID 39181888, 2024). "In strong support of its tumor suppressor function, loss of RFX7 accelerated B cell lymphomagenesis in mouse models." (PMID 39181888, 2024). "We identify novel target genes linked to RFX7’s tumor suppressor function and underscoring its potential role in neurological disorders." (PMID 36864036, 2023). "We have also identified genes directly and indirectly regulated by RFX7 genome-wide, including genes involved in neuronal processes, metabolic regulation, and tumor suppressor genes such as PDCD4, DDIT4, and PIK3IP1." (PMID 39181888, 2024). "The evolutionarily well-conserved transcription factor RFX7 was identified in 2008, and it was only recently that RFX7 was identified as a tumor suppressor when a larger number of whole-genome sequencing analyses of cancer samples became available." (PMID 39181888, 2024). "We recently revealed that RFX7 controls the expression of several known tumor suppressors, further substantiating its tumor suppressor function." (PMID 39181888, 2024). "Together, the novel RFX7 targets yield additional evidence for RFX7’s role in tumor suppression and neurological disorders and provide promising starting points to further investigate its function." (PMID 36864036, 2023). "Together, our transcriptome analysis of RFX7 knock-out U2OS cells combined with RFX7 DNA binding data revealed novel target genes contributing to RFX7’s roles as a tumor suppressor and potential neuronal regulator." (PMID 36864036, 2023). "The 33 novel RFX7 targets comprise multiple genes with known roles in tumor suppression or neuronal processes." (PMID 36864036, 2023). "Altogether, these data validate Rfx7 and Phip as potent tumor suppressors in B-cell lymphomagenesis." (PMID 30926791, 2019). "CRISPR/Cas9 targeting of Rfx7 in HSPCs confirmed its predicted function as a DLBCL tumor suppressor." (PMID 30926791, 2019). "Recent research indicates that the understudied transcription factor RFX7 may have a role in tumor suppression, metabolic control, and neuronal fitness." (PMID 36864036, 2023). "Finally, we were also able to identify a number of TFs of interest, including RFX3 and RFX7 from snATAC-seq analysis of the recurrent tumor autopsy specimen." (PMID 35941215, 2022). "Transposon insertion patterns in Rfx7 suggest a tumor suppressive function." (PMID 30926791, 2019). "While RFX3 was differentially expressed across the tumor-cell populations, RFX7 was not and would have been missed using snRNA-seq analysis alone, further highlighting the value of multi-omic data analysis in identifying potential TF targets." (PMID 35941215, 2022).
cancer (4 papers, 2010 to 2026). A tumor composed of atypical neoplastic, often pleomorphic cells that invade other tissues. "For example, RFX7 mutations have been implied to be cancer drivers in Burkitt lymphoma and chronic lymphocytic leukemia." (PMID 39181888, 2024). "RFX7 may be an attractive target for cancer therapy because it is mutated in a relatively small number of cancers but appears to be inactivated in many cancers." (PMID 39181888, 2024). "Besides cancer, RFX7 has been implicated in organismal development, neurological disorders, metabolic disorders, and immune cell maintenance." (PMID 39181888, 2024). "In addition to cancer, RFX7 has been associated with metabolic disorders, neurological disorders, and organismal development and cellular differentiation." (PMID 36864036, 2023). "Intriguingly, RFX7 target gene expression correlated with better patient prognosis across multiple cancer types, indicating a frequent dysregulation of RFX7 signaling in cancer even when RFX7 is not mutated." (PMID 36864036, 2023). "Thus, the identification of RFX7 target genes is an important step to better understand the mechanisms contributing to RFX7’s role in the suppression of cancer and other diseases." (PMID 36864036, 2023). "Furthermore, we found RFX7 target genes to be dysregulated in numerous cancer types also beyond the hematological system." (PMID 36864036, 2023). "In addition, RFX7 appears to be deactivated in many cancers in which it is not mutated, making RFX7 reactivation an intriguing target for cancer therapy." (PMID 39181888, 2024). "To date, none of the 6 other HRneg/Tneg signature genes not functionally linked to chemokine pathways (PRRG3, RFX7, MATN1, SSX3, HRBL, and ZNF3) has shown any reported association with cancer." (PMID 20946665, 2010).
infection (2 papers, 2017 to 2023). The state of being infected such as from the introduction of a foreign agent such as serum, vaccine, antigenic substance or organism. "We find that the concentrations of two cell cycle-regulated proteins at the time of infection (RFX7 and geminin) are predictive of successful gene expression by HSV-1." (PMID 29114028, 2017). "We identify two proteins, RFX7 and geminin, whose levels at the time of infection correlate with successful initiation of gene expression." (PMID 29114028, 2017). "The dynamics of geminin and RFX7 in cells following infection seem to be different, probably representing a random difference in the position of these cells along the cell cycle." (PMID 29114028, 2017). "Moreover, the RFX7 phosphorylation level was increased by either UL97-expressing or HCMV-infection in NPCs, suggesting that pUL97 induces RFX7 phosphorylation to drive SOCS3 transcription." (PMID 36753521, 2023).
hematopoietic cancers (1 paper, 2024). "The greater importance of RFX7 in this interaction could explain why only RFX7 mutations, but not ANKRA2 mutations, have been associated with driver events in hematopoietic cancers." (PMID 39181888, 2024).
metabolic disorders (1 paper, 2023). "Previous reports suggested that RFX7 may also have a role in neurological and metabolic disorders." (PMID 36864036, 2023).
neurological disorders (1 paper, 2023). "Moreover, supporting RFX7’s potential role in neuronal development and neurological disorders, we identified regulators of neuronal processes among the novel RFX7 targets, such as JUN, SYNPO, PPP3CA, and PPP2R5D." (PMID 36864036, 2023).
RFX7 also shares sentences with these, for which no sentence is quoted: leukemia (1 paper); maturity-onset diabetes of the young (1); Obesity (1); uveal melanoma (1).